CAV1 (caveolin 1)
Diseases named in the same sentence as CAV1 in open-access papers (continued):
Sharing a sentence is not in itself a finding about the gene and the disease.
pancreatitis (3 papers, 2018 to 2023). Inflammation of the pancreas. "CAV1-mediated control of YAP activity was validated in vivo in a model of pancreatitis-driven acinar-to-ductal metaplasia." (PMID 30404014, 2018). "Taken together, these data suggest that CAV1 is required for YAP activation in the context of caerulein-induced pancreatitis and that this activation correlates with increased ADM in pancreatic tissue." (PMID 30404014, 2018). "Similarly, YAP mechano-response was shown to be positively regulated by the integral membrane protein Caveolin-1 (CAV1) on stiff substrates through an actin dependent mechanism driving acinar-to-ductal metaplasia (ADM) in pancreatitis, a benign inflammatory pancreatic disease." (PMID 34298706, 2021). "The study was conducted in the context of pancreatitis, since YAP is required for pancreatitis-induced acinar-to-ductal metaplasia, and upregulation of Caveolin-1 expression decreases survival of pancreatic cancer." (PMID 37894323, 2023). "We further demonstrate CAV1-dependent positive regulation of YAP in vivo, showing that Cav1-knockout (Cav1KO) pancreatic parenchyma fails to upregulate YAP in response to induced pancreatitis and exhibits blunting of changes associated with YAP activation, such as ADM." (PMID 30404014, 2018).
pituitary adenoma (3 papers, 2007 to 2021). "Our data show that increased caveolin-1 expression sensitizes pituitary adenoma GH3 cells to apoptosis induced by bromocriptine treatment and clarifies the molecular mechanism of bromocriptine therapy of pituitary adenoma." (PMID 17331262, 2007). "In summary, the present results demonstrate that caveolin-1 expression is induced after bromocriptine treatment in rat pituitary adenoma cells." (PMID 17331262, 2007). "In the present study, we investigated the effects of caveolin-1 on pituitary adenoma shrinkage in response to bromocriptine treatment at clinically-relevant concentrations in GH3 cells." (PMID 17331262, 2007). "Moreover, exogenous overexpression of caveolin-1 increases apoptosis of pituitary adenoma cells and enhances bromocriptine-induced cell apoptosis." (PMID 17331262, 2007). "Our results reveal that caveolin-1 increases sensitivity for apoptosis induction in pituitary adenoma GH3 cells and may contribute to tumor shrinkage after clinical bromocriptine treatment." (PMID 17331262, 2007). "Rat pituitary adenoma GH3 cells, which express endogenous caveolin-1, exhibit increased apoptosis and shrinkage after exposure to bromocriptine." (PMID 17331262, 2007).
rectal cancer (3 papers, 2009 to 2021). A primary or metastatic malignant neoplasm that affects the rectum. "Caveolin‐1 (Cav1) was implicated in tumour cell migration and metastasis, which was validated as an independent predictor of decreased survival in rectal cancer." (PMID 34613665, 2021). "According to literature validation, we detected some rectal cancer‐related mRNAs including PRKCB, NCAM1, ZEB1, PCDH7, Cav1 and FGF2 in the subnetwork." (PMID 34613665, 2021).
retinoblastoma (3 papers, 2012 to 2025). A malignant tumor that originates in the nuclear layer of the retina. "CAV1 expression was increased in epithelioid melanoma but reduced in retinoblastoma, mixoid, and spindle melanomas." (PMID 41374987, 2025). "The authors showed that Cav-1(−/−) MSFs share a number of properties with human CAFs, including similar gene profiles, the functional inactivation of the retinoblastoma (RB) tumor suppressor and the functional characteristics of myofibroblasts." (PMID 25202343, 2014). "We examined five proteins that help cells handle nutrients and signals, Megalin, Cubilin, Caveolin-1, GIPC1, and DAB2IP, in normal eye tissue, retinoblastoma, and different forms of choroidal melanoma." (PMID 41374987, 2025). "However, in retinoblastoma (GSE208143), LRP2 was downregulated, while CUBN, CAV1, GIPC1, and DAB2IP were upregulated." (PMID 41374987, 2025).
schwannoma (3 papers, 2013 to 2025). A benign, usually encapsulated slow growing tumor composed of Schwann cells. "CAV1 has also been reported in relation to Schwann cell signaling and myelination, and its dysregulation may reflect a role in schwannoma pathophysiology." (PMID 41231782, 2025). "Two blue module genes that are essential to ECM, CAV1 and CAV2, were conserved in both hiPSC and mouse derived SCs and may be linked to NF2-associated vesicle trafficking as previously shown in schwannoma." (PMID 40585242, 2025). "Our results concur with earlier array analysis data on schwannomas, such as caveolin-1 (CAV1) downregulation, as well as with other studies conducted, using techniques such as qRT-PCR [i.e., neuregulin 1 (NRG1)-ErbB2-ErbB3 upregulation] and immunohistochemistry analysis (CCND1 upregulation)." (PMID 23354516, 2013). "Due to its involvement in several deregulated signals, the MET pathway seems to exert a pivotal role in schwannoma development and CAV1 may also exert its protumoral effect in this manner." (PMID 23354516, 2013). "Our results demonstrated that the mRNA levels of both transcripts were downregulated, suggesting that there may be a mechanism by which AR and CAV1 are related to the development and/or maintenance of schwannomas." (PMID 23354516, 2013). "Therefore, HEPACAM gene overexpression concomitant with CAV1 downregulation may participate in schwannoma development and/or maintenance and some members of the immunoglobulin superfamily appear deregulated in schwannomas." (PMID 23354516, 2013). "In our series, 5 HSPs were deregulated (HSPA12A: 3.31-fold, p=4.34e-4; HSPA13: 2.54-fold, p=0.0035; HSPA4L: 2.38-fold, p=1.17e-4; HSPB6: −2.19-fold, p=5.76e-4; HSPB8: −3.77-fold, p=0.001), suggesting that the CAV1/HSPs interaction may also play a role in schwannomas." (PMID 23354516, 2013). "Therefore, in schwannoma cells, apoptosis mediated by CAV1-AR-PAWR does not seem to occur due to the downregulation of PAWR mRNA in the tumor cells." (PMID 23354516, 2013). "We therefore selected genes that were well-established as deregulated in these tumors to verify our results and then focused on deregulated genes in other tumors, as well as in our series, that had been insufficiently studied or not studied at all in schwannomas, such as MET, AR or CAV1." (PMID 23354516, 2013).
skin tumor (3 papers, 2016 to 2024). "In this study, they examined the effects of Cx43 interaction with the skin tumor suppressor caveolin-1 (Cav-1) in rat epidermal keratinocytes (REK)." (PMID 27229305, 2016).
soft tissue sarcoma (3 papers, 2011 to 2014). A malignant neoplasm arising from muscle tissue, adipose tissue, blood vessels, fibrous tissue, or other supportive tissues excluding the bones. "However, as demonstrated in some bone and soft tissue sarcomas, CAV1 may have a key role in their malignant progression." (PMID 21471610, 2011).
systemic lupus erythematosus (3 papers, 2021 to 2025). An autoimmune multi-organ disease typically associated with vasculopathy and autoantibody production. "In addition, CAV1 might also promote systemic lupus erythematosus through regulating pathways of T cell costimulation, lymphocyte costimulation, and B cell receptor signaling." (PMID 35127724, 2021).
T-cell lymphomas (3 papers, 2015 to 2016). "Regarding a shared activated phenotype for T-cell lymphomas, of the observed upregulated genes, two (CAV1 and ENAH) have been implicated in cytoskeletal remodeling (and therefore, cellular migration and immune synapse formation) following TCR-ligation." (PMID 26566034, 2015). "Future study investigating the clinical implications of CAV1 expression in mature T-cell lymphomas is warranted." (PMID 26566034, 2015). "Strikingly, an uncharacterized long, intergenic non-coding RNA (LINC00273) was found to be expressed 3-fold higher in CAV1-Low T-cell lymphoma samples compared to CAV1-High." (PMID 26566034, 2015). "Further, stratifying malignant samples in accordance with high and low CAV1 expression revealed that higher expression of CAV1 in mature T-cell lymphomas is analogous with an enhanced inflammatory and invasive gene expression profile." (PMID 26566034, 2015). "Caveolin-1 was upregulated, albeit with a heterogeneous nature, across all mature T-cell lymphoma subtypes, a finding confirmed using immunohistochemical staining on an independent sampling of mature T-cell lymphoma biopsies (n = 65 cases)." (PMID 26566034, 2015). "Analysis of CAV1 expression using 212097_at probe signal intensity revealed that all mature T-cell lymphoma subtypes analyzed have a higher mean expression of CAV1 (p < 0.001, FDR < 0.001) as compared to healthy CD4+ and CD8+ T-cell controls." (PMID 26566034, 2015). "The existence of the heterogeneity of CAV1expression in T-cell lymphomas was further solidified with our immunohistochemical results, with 55% (36/65) of tumor biopsies harboring lymphoid staining of CAV1." (PMID 26566034, 2015). "As CAV1 is overexpressed in mature T-cell lymphomas, the tumor microenvironment adopts a gene expression profile indicative of increased inflammation and metastatic potential." (PMID 26566034, 2015). "Finally, we characterize a role for CAV1 within the tumor microenvironment, wherein higher CAV1 expression among mature T-cell lymphomas coincides with a more inflammatory and invasive gene expression profile." (PMID 26566034, 2015). "In our analyses, CAV1 was upregulated in each T-cell lymphoma subtype." (PMID 26566034, 2015). "Using this threshold, 67% (125/187) of mature T-cell lymphoma samples were classified as CAV1-High." (PMID 26566034, 2015). "However, further analysis is required for confirmation of a role for CAV1 in disease progression in T-cell lymphomas." (PMID 26566034, 2015). "Therefore, we decided to further investigate the differences between CAV1-High and CAV1-Low expressing mature T-cell lymphoma samples in an effort to characterize the impact of CAV1 on the tumor microenvironment (TME)." (PMID 26566034, 2015). "Our results demonstrate interplay between CAV1 and BCL10 in T-cell lymphomas and warrants further investigation." (PMID 26566034, 2015). "For each T-cell lymphoma subtype: 77% (33/43) of AITL samples, 47% (21/45) of ALCL samples, 85% (11/13) of ATLL samples, 75% (6/8) of HSTL samples, and 69% (54/78) of PTCL-NOS samples were classified as CAV1-High." (PMID 26566034, 2015).
uveal melanoma (3 papers, 2018 to 2025). A melanoma derived from melanocytes of the uveal tract. "Given this duality, profiling CAV1 in ocular tumors is warranted, as primary studies in uveal melanoma have linked CAV1 expression to PI3K signaling and vasculogenic mimicry, and have shown distinct expression patterns compared to those in cutaneous melanoma." (PMID 41374987, 2025). "Our results parallel this observation, as epithelioid melanomas–the most aggressive subtype–also showed increased CAV1 protein, supporting the link between Cav-1 and tumor progression in uveal melanoma." (PMID 41374987, 2025). "To evaluate the prognostic relevance of LRP2, CUBN, DAB2IP, GIPC1, and CAV1 in uveal melanoma, we performed overall survival analysis using the GEPIA2 online platform." (PMID 41374987, 2025). "The results showed that Cav-1 is essential for U251 cell proliferation and VM formation, which is in agreement with the findings in uveal melanoma." (PMID 34287575, 2021). "Incorporating LRP2, CUBN, Caveolin-1, GIPC1, and DAB2IP into biomarker-driven clinical trial design could enhance risk stratification in uveal melanoma and RB and support the development of prognostic signatures that distinguish aggressive from indolent disease." (PMID 41374987, 2025). "Moreover, based on the findings that Cav-1 expression is correlated with PI3K activity and VM formation in primary uveal melanoma tissues, the expression of Akt, the major downstream effector of PI3K, was evaluated." (PMID 34287575, 2021).
abdominal aortic aneurysm (2 papers, 2020 to 2024). Enlargement and ballooning of the vessel that supplies arterial blood to the abdomen, pelvis and legs. "Previous studies indicate that Cav1 plays a significant role in regulating both eNOS and TGF-β signaling within the vascular wall and in the development of angiotensin II (AngII)-induced abdominal aortic aneurysms (AAAs)." (PMID 39684412, 2024).
Achalasia (2 papers, 2016 to 2021). A disorder of esophageal motility characterized by the inability of the lower esophageal sphincter to relax during swallowing and by inadequate or lacking peristalsis in the lower half of the body of the esophagus. "This investigation found that Caveolin1 (CAV1) involving in the calcium signaling pathway could be a significant target of hsa-miR-3609 and hsa-miR-194-5p which are differentially expressed in the achalasia tissues of the patients." (PMID 34377051, 2021). "We observed a number of sequences involving the calcium signaling pathway (ie, CACNA1C, CACNB2, KCNMA1, CHRM2, CAV1, and NCS1) that were differentially expressed and were able to characterize these genes into possible functions related to achalasia pathogenesis." (PMID 27511445, 2016).
acute lung injury (2 papers, 2022 to 2026). A condition of lung damage that is characterized by bilateral pulmonary infiltrates (pulmonary edema) rich in neutrophils, and in the absence of clinical heart failure. "Secondly, knocking out the Cav‐1 E3 ubiquitin ligase, ZNRF1could reduce pulmonary inflammatory infiltration in LPS‐induced acute lung injury mice." (PMID 34889029, 2022).
adenoma (2 papers, 2002 to 2019). A neoplasm arising from the epithelium. "On the other hand, all cases of follicular carcinoma and adenoma were classified as negative for caveolin-1." (PMID 11953823, 2002).
AIDS (2 papers, 2017 to 2025). A syndrome resulting from the acquired deficiency of cellular immunity caused by the human immunodeficiency virus (HIV). "Cav‐1 is a crucial player in the pathogenesis of many AIDs and has the potential to serve as both a diagnostic marker and a therapeutic target for these diseases." (PMID 40778471, 2025). "Cav‐1 emerges as a promising therapeutic target for AIDs, with potential in regulating immune tolerance and reducing inflammation." (PMID 40778471, 2025). "As research into Cav‐1 deepens, it may offer new insights into the diagnosis, treatment, and drug sensitivity of AIDs, emerging as a promising target for future therapeutic strategies." (PMID 40778471, 2025). "With the deepening of the study, Cav‐1 could open new avenues for diagnosing and treating AIDs, enhancing drug sensitivity, and emerging as a novel target for the treatment of various AIDs." (PMID 40778471, 2025). "The study of Cav‐1 and the occurrence and development of AIDs is still in the primary stage." (PMID 40778471, 2025). "Cav‐1 is increasingly recognized as a biomarker in certain AIDs and may become pivotal in treating these diseases in the future." (PMID 40778471, 2025). "Recently, research on Cav‐1 in autoimmune diseases (AIDs) has garnered significant interest." (PMID 40778471, 2025). "Given its potential role in AIDs, Cav‐1 may serve as a clinical biomarker for diagnosis and monitoring." (PMID 40778471, 2025). "Since increased ROS production enhances Cav-1 expression, which is a key player of cellular senescence, there may be a link to non-AIDS related risks with Cav-1 mediated cellular senescence." (PMID 28587148, 2017). "The p‐Cav‐1 plays a critical role in apoptosis within the lesions observed in EAN, offering valuable insights into its involvement in inflammatory cell death and highlighting its potential as a therapeutic target for AIDs." (PMID 40778471, 2025).
airway hyperresponsiveness (2 papers, 2013 to 2015). "Moreover, the role of caveolin-1 in airway hyperresponsiveness has become highly controversial due to the view that caveolin-1 is related to the regulation of contractile mechanisms, including, proteins that participate in intracellular Ca2+ mobilisation." (PMID 25977751, 2015). "The development of airway hyperresponsiveness in allergen (ovalbumin)-challenged mice without caveolin-1 has been observed, and Hsia and colleagues have found the absence of caveolin-1 induced airway hyperresponsiveness in endotoxin (lipopolysaccharide)-challenged mice." (PMID 25977751, 2015).
alopecia (2 papers, 2021 to 2022). Hair loss usually from the scalp. "It should be noted that these data need to be validated in human hair follicles in order to confirm the physiological relevance of elevated Cav1 expression on IP collapse in scarring alopecia." (PMID 34069454, 2021). "CAV-1 expression is upregulated in the bulge area of patients with frontal fibrosing alopecia compared to healthy controls, and it is speculated that CAV-1 upregulation may contribute to the pathogenesis of alopecia." (PMID 36532050, 2022). "Therefore, we hypothesize that Cav1 may be an unrecognized, important player in the pathobiology of cicatricial alopecias, and particularly, in FFA, which is currently considered as the most common type of primary lymphocytic scarring alopecia in the world." (PMID 34069454, 2021).
ANCA associated vasculitis (2 papers, 2013 to 2015). "In summary, this is the first study to describe the association between CAV1 variation and the outcomes of patients with ANCA associated vasculitis." (PMID 23894397, 2013).
aortic aneurysm (2 papers, 2015 to 2024). A ruptured aneurysm located in the wall of the proximal portion of the descending aorta proceeding from the arch of the aorta. "Further investigations using a more specific and targeted genetic manipulation of the Cav1 gene would elucidate the mechanisms in the regulatory action of Cav1 on eNOS in the mouse model of MFS-associated aortic aneurysms." (PMID 39684412, 2024). "A tissue-specific approach would provide a more detailed understanding of the role of Cav1 in specific cell types and their contribution to MFS-associated aortic aneurysms." (PMID 39684412, 2024). "We also demonstrate that caveolin-1 expression is reduced in yet another form of arterial injury, namely aortic aneurysms." (PMID 26244347, 2015). "A decrease of CAV1 was observed concomitant with a decrease of the smooth muscle marker calponin in aortic aneurysms from mice (C57Bl/6) infused with angiotensin II." (PMID 26244347, 2015). "The study of Cav1 in the context of MFS-associated aortic aneurysms is not only important for a deeper understanding of the disease’s pathophysiology, but also holds promise for innovative treatments." (PMID 39684412, 2024). "We also examined caveolin-1 and cavin-3 staining in angiotensin II-induced aortic aneurysms in mice (the cavin-1 antibody was not ideal for staining of mouse tissues)." (PMID 26244347, 2015).
arterial disease (2 papers, 2013 to 2017). "A recent clinical report has suggested that arterial diseases are associated with disturbed interaction between Cav-1 and eNOS." (PMID 23469284, 2013).
Arthritis (2 papers, 2023 to 2025). Inflammation of a joint. "The P. goldsteinii enriched in Guizhi Shaoyao Zhimu Decoction (GSZD) secretes OMVs that migrate to the joints, activating the Cav-1-Nrf2 axis, thereby reducing the formation of NETs and alleviating arthritis." (PMID 41019532, 2025). "AHR, CAV1, CRP, CXCL2, IRF1, SPP1 and other targets play important roles in the pathogenesis of arthritis and can be used as key targets for the treatment of arthritis." (PMID 37637408, 2023).
autism (2 papers, 2018 to 2022). Persistent deficits in social interaction and communication and interaction as well as a markedly restricted repertoire of activity and interest as well as repetitive patterns of behavior. "Interestingly, human Cav1 is located at 7q31.1, part of autism-linked locus 9 (Auts9), immediately upstream of MET, which shows direct pretranscription start-site mutations associated with ASD." (PMID 29379878, 2018).